IL15 (interleukin 15)
Diseases named in the same sentence as IL15 in open-access papers (continued):
Sharing a sentence is not in itself a finding about the gene and the disease.
tumor (continued). "Interestingly, in our study, the NB γδT cells supposedly having dull responsiveness to IL-15 signaling was still capable of killing target tumor cells, in a level similar to that from HC γδT cells." (PMID 35351861, 2022). "One way to improve the in vivo persistence of CAR-NK cells in the suppressive tumor microenvironment could be by inducing the expression of stimulatory cytokines, such as IL-2, IL-7, IL-15, and IL-21." (PMID 35203609, 2022). "In NSG (NOD scid gamma) mice bearing SKOV-3 tumors, although in combination with Herceptin treatment, NK cells cultured for 7 days with CHIR99021 showed more consistent tumor control compared to NK cells expanded for 7 days in DMSO or grown overnight in vitro with IL-15 stimulation." (PMID 36348457, 2022). "Culture of CAR T cells with IL-7 and IL-15 during manufacturing has been shown to enhance T cell differentiation toward a central memory (Tcm) phenotype, enhancing the persistence and anti-tumor efficacy of CAR T cells in vivo and prolonging survival in murine models of B-ALL29." (PMID 35697686, 2022). "The telomerase reverse transcriptase (TERT)-positive tumor treated with CCL20/IL15-armed oAd that replicated under control of the TERT promoter plus NK showed significantly higher antitumor efficacy than either of the treatments alone and induced tumor-specific cytotoxicity of CTLs." (PMID 36091031, 2022). "Similarly, IL-15 in combination with IL-2 boosted the proliferation as well as the in vitro anti-tumor activity of ZOL-expanded Vδ2 T cells." (PMID 36429001, 2022). "In addition, IL-15 can increase the infiltration of NK cells in the tumor and improve the survival rate in the treatment of GC liver metastasis–bearing mice." (PMID 36225938, 2022). "Interestingly, both NK cells and macrophages were shown to be necessary, but not alone sufficient, for an optimal ADCC upon the treatment with IL-15 and human IgG1 therapeutic antibodies in mouse tumor models in vivo." (PMID 36300122, 2022). "They showed that CAR-T cells that coexpress IL-15 and/or IL-21 were effective against tumor cells." (PMID 36172343, 2022). "Eliminating lymphocytes in the tumor microenvironment facilitates infused cells’ trafficking to the tumor site and their accessibility to various homeostatic cytokines, including IL-2, IL-7, and IL-15, while also reducing immunosuppressive cells that impair antigen-presentation." (PMID 35515137, 2022). "Interestingly, the addition of IL-2 and IL-15 to the tumor cells contributed to the enhancement of the lysis of tumor cells through increased NK cell activity." (PMID 36010854, 2022). "HODHBt improves the ability of IL-15-activated NK cells to kill tumor cells and HIV-infected cells." (PMID 35867565, 2022). "Previous research revealed that IL-15 could promote cell proliferation, the anti-tumor function of γδT cells, and enhance the response of γδT cells to microbial pathogens." (PMID 35351861, 2022). "They found that CD40 agonist/IL15 is the most effective for suppressing tumor growth." (PMID 35453676, 2022). "Moreover, elevated IL-6 and decreased IL-15 in pre-cachetic and cachetic patients can alter the function of immune cells, which resulted reduced anti-tumor effect." (PMID 35538112, 2022). "IL-15 stimulates tumor-specific T-cell responses, increases cellular growth, inhibits apoptosis, and enhances immune cell activation, and as a consequence, promotes anti-tumor responses." (PMID 35664073, 2022). "Considering the complexity of IL-15 biology, there is no direct evidence showing IL-15 is the causation of tumor progression or evasion so far." (PMID 35806311, 2022). "Furthermore, this control of tumor growth was mediated via a STING/IL-15/CD8/NK cell axis wherein the depletion of any of these elements rendered particle treatment ineffective." (PMID 36059473, 2022). "However, there was a significant reduction in tumor growth kinetics in HSC‐engrafted NSG‐Tg(Hu‐IL15) mice compared to HSC‐engrafted NSG mice." (PMID 35959876, 2022).
tumor (continued). "Furthermore, IL-15 enhances the anti-tumor efficacy of the extracellular vesicles derived from NK cells, showing higher cytolytic activity against GBM." (PMID 35681612, 2022). "Similarly, NK cell-mediated suppression controlled by tumor-derived vesicles proved to be therapeutic in instances of AML accompanied by the opposition of suppression by interleukin-15." (PMID 36032679, 2022). "Since IL-15 is a critical cytokine required to maintain NK cells’ survival, proliferation, and activation, there has been an ongoing quest to elevate the persistence and anti-tumor activity of NK cell products." (PMID 36428748, 2022). "IL-15 can maintain NK cell populations and tumor killing ability in the TIME." (PMID 36582246, 2022). "Further studies are required to determine whether increased CD39 expression on CAR-T cells encapsulated in PNP-1-5 hydrogels with IL-15 is due to increased tumor reactivity, induction by IL-15 signaling, increased CAR-T exhaustion, or some other mechanism." (PMID 35394838, 2022). "Unfortunately, the recombinant human IL15 protein used in clinical trials, to treat cancer patients, undergoes a rapid renal clearance and has a short plasma half‐life which diminishes its anti‐tumour effects." (PMID 35758207, 2022). "Alternatively, oncolytic virotherapy has also exploited the benefits of IL-15 immunostimulation, with several studies focused on genetically engineered viruses armed with IL-15, either alone or in combination with other molecules, to augment anti-tumor responses." (PMID 36231109, 2022). "Another cytokine, IL-12, is of a similar anti-tumor function to IL-15." (PMID 36246629, 2022). "Thus, OMCPmutIL-2–expanded CD8+ T cells outperformed T cells expanded in IL-2 or IL-15 in multiple murine and human tumor models." (PMID 35603788, 2022). "CAR-T cells with the combined expression of IL-15 and IL-21 showed a less differentiated profile and longer survival in repeated exposures to tumor cells, in addition to maintaining the expression of T-cell factor-1 (TCF-1), an important factor for the development and survival of T cells." (PMID 36172343, 2022). "used IL-15-pretreat NK cells significantly enhances the anti-tumor potency of NK cell-EVs." (PMID 35915054, 2022). "However, certainly physical activity can also make a significant contribution to tumor therapy via IL-15 release and the activation of CD8+ cells." (PMID 35995771, 2022). "In addition, in CRC patients, IL-15 was shown to recover anti-tumor functions of infiltrating NK cells in liver metastases." (PMID 35891197, 2022). "Notably, the application of IL-15, which is reported to induce a better anti-tumor response, is always accompanied by serious toxicity." (PMID 36167591, 2022). "Numerous efforts have been devoted to optimizing the structure of CAR NK to alleviate immunosuppression and enhance their anti-tumor activity, including using advanced genetic engineering techniques to enable NK cells to simultaneously express IL-15 or knock out checkpoint molecules." (PMID 36428748, 2022). "Furthermore, we investigated the involvement of the IL-15/IL-15RA pathway in H89-mediated tumor growth inhibition in CT26 tumor-bearing mice." (PMID 35572581, 2022). "In the future, our bispecific antibody may combine with cytokines enhancing NK proliferation and function such as interleukin-2 and interleukin-15 to potentiate NK-mediated ADCC against antibody-coated tumor cells and T regular cells." (PMID 36289396, 2022). "Their expansion and effector differentiation are dependent on IL-15, which is produced by many cancer cells; interestingly, inducible activation of IL-15 signaling in adoptively transferred ILTCK progenitors suppresses tumor growth while deletion of IL-15 in cancer cells increases tumor growth." (PMID 36142818, 2022). "Tumor cells are lysed by IL-15-induced NK cells in patients." (PMID 35463956, 2022).
tumor (continued). "In addition to EVs, other factors secreted by CAR-T cells, such as IL-12, IL-15, and IL-18, play roles in killing tumor cells." (PMID 35410257, 2022). "In tumors lacking IL-15 production, g1 ILCs appear to be associated with negative outcomes and should be depleted, or manipulated to re-establish their anti-tumor functions." (PMID 36372017, 2022). "Subsequently, cytokine secreted from T cells in response to those tumor cells was increased, and those cytokines including IL‐2, IL‐7, IL‐15, and interferon gamma (IFN‐g), could induce PD‐L1 expression." (PMID 34907653, 2022). "Additionally, the combination therapy of IL-15 and IL-21 was used in rhabdomyosarcoma to enhance anti-tumor response." (PMID 36246629, 2022). "IL-15, a type I cytokine together with IL-2, IL-4, IL-7, IL-9, and IL-21, promotes survival of T, B, and NK cells by binding to IL-15α, encoded by IL15RA, negatively regulating both carcinogenesis and tumor growth." (PMID 36432658, 2022). "Here the NK cell interaction and the presence of macrophages was shown to be indispensable for the anti-tumor efficacy, as the clodronate treatment leading to the elimination of macrophages in vivo abrogated the IL-15 induced FcγRIV and NKG2D expression on NK cells." (PMID 36300122, 2022). "In our study, we found that IL-15 combined with IL-15Ra reduced adverse events significantly during CAR-T therapy that had the potential ability to prolong the survival rate of tumor-treated mice with the health liver and lower GVHD score, indicating a novel function of IL-15Ra." (PMID 36167591, 2022). "With improved immune cell activation and migration, IL-15 is involved in anti-tumor immunity." (PMID 36467072, 2022). "Interestingly, using IL-2 or IL-15 cytokines to stimulate NK cells can significantly enhance the anti-tumor ability of their derived EVs." (PMID 35915054, 2022). "Other molecules that are being studied include NKTR-255, a novel polyethylene glycol-conjugate of rhIL-15, and NIZ985, a recombinant heterodimer of IL-15/IL15Rα, both of which have shown promising anti-tumor efficacy in a preclinical and phase I clinical trial, respectively." (PMID 36231109, 2022). "Moreover, we performed biodistribution with increasing doses of TPA and observed a significant dose‐dependent expression of IL15 mRNA by RGD4C.TPA.IL15IgK in tumours at 5 × 109, 1 × 1010 and 1 × 1011 TU/mouse (Fig EV4A)." (PMID 35758207, 2022). "The depletion however lowered the percentage and number of CD56dim/CD16+ NK cells within the tumor microenvironment to levels similar to those in NSG mice, suggesting that tumor killing in NSG‐Tg(hu‐IL15) mice was a result of increased NK cell numbers and function." (PMID 35959876, 2022). "However, studies have indicated that IL-15 can lead to both a favourable and an unfavourable diagnosis, differing by the type of tumor." (PMID 32929618, 2021). "IL-15 is shown to regress tumors by activating the tolerogenic tumor-infiltrating cells (TIL)." (PMID 33953717, 2021). "Cyto-IL-15 Gen was previously shown to delay TRAMP-C2 tumor growth and increase mice survival." (PMID 34778376, 2021). "Whilst IL-2 and IL-15 overlap in several key functions, including supporting the proliferation and activation of NK cells, IL-2 can support the persistence of regulatory T cells (Tregs), which is an undesirable feature in the context of anti-tumour immunity." (PMID 35008227, 2021). "In a PC mouse model, the simultaneous administration of IL-15, anti-CTLA-4, and anti-PDL-1 was associated with increased number of CD8+ T cells, T cell lytic activity, and IFN-γ release, decreased tumor growth, and improved mice survival (compared to IL-15 alone)." (PMID 34830179, 2021). "IL-15 values were also significantly decreased in patients with a Grade 2 tumor." (PMID 32929618, 2021). "In contrast, IL-15 stimulation resulted in tumor regression in all mice." (PMID 34081628, 2021).
tumor (continued). "Additionally, treatment with 10 μg cyto-IL-15 Gen delayed tumor growth by 55% (p < 0.001) compared with vehicle." (PMID 34778376, 2021). "The ADCC induced by the cetuximab and IL-2 or IL-15 combination was more evident, since the combination reduced the xenograft tumor volume with an increase in infiltrating NK cells, whereas no significant induction of direct antiproliferative effects on the tumor was observed." (PMID 34207383, 2021). "In line with our long-term goal to use TIL-PDX mice to develop effective primary combination immunotherapies, we examined if the addition of IL-15 stimulation to PD-1 blockade augments the antitumor response of tumor-exhausted CTLs and NK cells in our TIL-PDX-LUAD model." (PMID 34081628, 2021). "However, recent preclinical studies have shown that other gamma-chain cytokines (such as IL-7 and IL-15) promote a less-differentiated T cell phenotype, resulting in longer persistence and better anti-tumor effects in comparison to IL-2." (PMID 34503109, 2021). "Diminished miR-29b reportedly induced the accumulation of tumor-promoting protein BRD4, which bound acetylated histones throughout the genome to regulate other tumor-related genes and highly activate IL-15 signaling, which, in turn, led to aberrant expression of miR-29b15." (PMID 33628583, 2021). "The proinflammatory cytokine IL-15 (useful for lymphocytes’ and NK cells’ recruitment) disappeared significantly in all the tissues investigated: plasma, tumour, contralateral mammary gland, and inguinal adipose tissue for the EE group compared to the SE group." (PMID 35008220, 2021). "The decrease in expression in our RNA-Seq data supports that IL-15 may play a role in the loss of CD8+ T cells that we describe in both the stroma and target of EAC tumor tissues observed in our multiplex IHC results." (PMID 33290281, 2021). "Similarly, a variety of different ILs, such as IL-2, IL-15, IL-27, and IL-6, play an important role in tumor microenvironment and immunotherapy." (PMID 34497605, 2021). "Several interventions combining IL-15 agents with checkpoint inhibitors, antibodies stimulating immune cell functions (e.g., anti-CD40, anti-CD16), monoclonal antibodies specific for tumor-associated antigens, and immunotoxins have been tested in preclinical models, with promising results." (PMID 33671252, 2021). "Additionally, we recently demonstrated that VitC increased the proliferation of IL-2/IL-15-expanded human γδ T cells, which was accompanied by a switch to memory T cell-like metabolism and improved anti-tumor function." (PMID 34899716, 2021). "IL-15 super-agonists and their role in the expansion of NK cells offers new approaches, which can be combined with existing treatment regimens with a promise of increased anti-tumor response." (PMID 34439191, 2021). "We tested here, using a replicating oncolytic virus (OV) that expresses IL-15/IL-15Rα (vvDD-IL15/Rα) in vivo, a strategy to enhance recovery of autologous tumor-specific memory CD8+ T cells which could be utilized for ACT." (PMID 33679747, 2021). "A potential impact of these studies is that blocking ADAM17 may provide a therapeutic approach to increase NK cell proliferation by IL-15 and their anti-tumor function in patients." (PMID 34367174, 2021). "High PD-L1 expression in tumours was associated with shorter progression-free survival (HR 3.25; 95% CI 1.39–7.61; P = 0.006) and low circulating levels of three multifunctional molecules; VEGF, TNF-β and IL-15 (P = 0.001)." (PMID 33446741, 2021). "Thus, IL-15 provides a favourable phenotype for transfer and promotes persistence, leading to greater anti-tumour potential." (PMID 33499101, 2021). "Notably, the combination of IL-15 stimulation and PD-1 blockade resulted in the most pronounced tumor regression in all treated TIL-PDX-LUAD mice, demonstrating that IL-15 stimulation prevents tumor escape from ICI and augments antitumor immunity." (PMID 34081628, 2021).
tumor (continued). "In addition, ARI2h cells expanded with IL-2, IL-15, or IL-15/IL-7 were injected into MM tumor-bearing mice to assess their in vivo efficacy." (PMID 34298748, 2021). "Additionally, recent phase I clinical studies found that ALT-803, an IL-15 superagonist, increased the number of circulating NK cells resulting in enhanced pro-inflammation and tumor growth arrest in patients with advanced sold tumors." (PMID 35127700, 2021). "In a previous study, we showed that the therapy targeting experimentally induced lung melanoma in mice with IL-15-encoding MYXV construct (vMyx-IL15Rα-tdTr) delivered by MSCs was effective and was able to reduce the tumor burden as well as triggering the inflow of CD8+ cells." (PMID 33808692, 2021). "IL-15 levels are being discussed to be used as a specific tumor biomarker for prognostic values." (PMID 32929618, 2021). "The cytokine IL-15 was also found to suppress tumor growth and prolong survival of mice." (PMID 33912464, 2021). "IL-15 stimulation prevents tumor escape from ICI and leads to sustained tumor regression." (PMID 34081628, 2021). "Further strengthening these data, implantation of previously frozen tumors, whereby TILs were killed from the freezing, resulted in ineffective treatment with IL-15/IL-15RαFc + PD-1 blockade in tumor-bearing PDXs, as demonstrated by their tumors growing 5-fold." (PMID 34081628, 2021). "In fact, many tumor therapies targeting IL-15 and IL-2 have shown positive therapeutic effects." (PMID 34497605, 2021). "Additionally, elevated levels of IL-15/IL-15R were found in tumor-dLNs, possibly indicating the formation of long-term memory." (PMID 34885215, 2021). "Furthermore, IFN-γ induces the expression of IL-12 and IL-15 in DCs, which induces anti-tumor responses through CD4+ TH1 and CD8+ T cells." (PMID 34439191, 2021). "However, when we compared lentivirally delivered 2K2 to exogenously added avelumab in the 3D tumor model, we observed that avelumab was more potent in stimulating tumor cell killing by IL-15-activated PBMCs." (PMID 34485603, 2021). "The impact of these findings is that blocking ADAM17 function in combination with IL-15 stimulation may provide a new therapeutic approach to increase NK cell proliferation and their anti-tumor function in patients." (PMID 34367174, 2021). "For example, a myokine, namely, interleukin (IL)-15 was reported to have an important role in T cell proliferation; exercise induces myokine IL-6, which releases and activates natural killer cells, thereby reducing tumor growth." (PMID 34551011, 2021). "In comparison to IL-2, IL-15 is far more effective at targeting NK cells for tumor therapy." (PMID 34725602, 2021). "It was found that the CAR-T/IL-15 group have the best anti-tumor effect." (PMID 34604060, 2021). "Nonetheless, an anti-tumour effect of IL-15 on the immune system has also been hypothesized in experimental trials and the activation of IL-15 is currently of major interest in several clinical Phase I trials." (PMID 32929618, 2021). "Several cytokines have been reported to support tumor growth in MF such as IL-13, IL-15 and IL-4." (PMID 33941102, 2021). "Similarly, a backpack loaded with an IL-15 super-agonist increased T cell-mediated tumor clearance by mouse CD8+ T cells and human chimeric antigen receptor (CAR)-T cell therapy in a mouse model." (PMID 34150739, 2021). "Moreover, we have shown that IL-15 localized in tumor lesions leads to an approximate 50% tumor reduction and increases survival of mice with prostate tumors with no apparent toxicity." (PMID 33777767, 2021). "In addition, our data provide novel insights into the utility of combining CX3CR1 antagonism with IL-15 to boost NK cell tumour-homing and tumour-killing in OAC patients." (PMID 35008227, 2021).